BANCR (BRAF-activated non-protein coding RNA)
Diseases named in the same sentence as BANCR in open-access papers (continued):
Sharing a sentence is not in itself a finding about the gene and the disease.
colorectal cancer (21 papers, 2014 to 2024). A primary or metastatic malignant neoplasm that affects the colon or rectum. "High lncRNA BANCR expression is associated with poor OS and linked to lymph node metastasis and poor survival in colorectal cancer." (PMID 39830506, 2024). "Recent studies have shown that non-coding RNA, especially lncRNA, is closely related to the occurrence of tumor chemotherapy resistance 27-31, and BANCR is associated with chemotherapy resistance in colorectal cancer." (PMID 34512168, 2021). "Fentanyl has decreased colony establishment and suppressed cell migration and invasion in colorectal cancer cells, whereas Ets-1 up-regulation has suppressed fentanyl-associated influences through down-regulation of BANCR (Li A.-x." (PMID 34409032, 2021). "Besides, BANCR has been commonly up-regulated in colorectal cancer samples in association with lymph node involvement and clinical stage." (PMID 34409032, 2021). "These analyses demonstrate that BANCR may be a good diagnostic biomarker for early-stage colorectal cancer." (PMID 25928067, 2015). "As low BANCR expression was associated with tumor size in colorectal cancer, we speculated that BANCR could play a significant role in tumor cell proliferation." (PMID 25928067, 2015). "Based on studies performed on colorectal cancer cells, it was demonstrated that BANCR induces (EMT) through a kinase-dependent mechanism regulated by MEK/extracellular signaling." (PMID 38601651, 2024). "BANCR is also upregulated in colorectal cancer plasma samples, and BANCR knockdown suppressed colorectal cancer progression and strengthened the chemosensitization of colorectal cancer cells to adriamycin." (PMID 37998732, 2023). "Another study has reported over-expression of BANCR in colorectal cancer cells and verified the impact of ectopic expression of BANCR in enhancement of migratory potential of human CRC Caco-2 cells." (PMID 34409032, 2021). "Up-regulation of BANCR has also inhibited colorectal cancer cell proliferation, activated G0/G1 arrest and enhanced apoptosis via influencing expression of p21 at posttranscriptional level." (PMID 34409032, 2021). "Another study in colorectal cancer cells has revealed the effects of Fentanyl on induction of BANCR over-expression and Ets-1 under-expression." (PMID 34409032, 2021). "BANCR has abnormal expression in various cancers, such as bladder cancer, colorectal cancer, melanoma, endometrial cancer, gastric cancer, and hepatocellular carcinoma." (PMID 30200918, 2018). "Hence, BANCR may be a significant diagnostic biomarker for colorectal cancer." (PMID 29212285, 2017). "Suppression of BANCR increases proliferation of colorectal cancer cells, partly via downregulation of p21." (PMID 27888635, 2017). "What’s more, overexpression of BANCR suppressed the growth of colorectal cancer cells in vitro and in vivo." (PMID 29212285, 2017). "Subsequently, aberrant lncRNA BANCR expression has been confirmed in papillary thyroid carcinoma, retinoblastoma, lung cancer, gastric cancer, and colorectal cancer." (PMID 26758762, 2016). "BANCR overexpression correlated with tumor stage and lymph node metastasis in colorectal cancer and contributed to cancer cell migration through inducing epithelial-mesenchymal transition." (PMID 26758762, 2016). "The similar result was also found in colorectal cancer that lower expression of lncRNA BANCR was related to increased tumor sizes." (PMID 27777512, 2016). "They showed that BANCR expression was significantly decreased in colorectal cancer, and when BANCR is overexpressed, it slowed down the growth of colorectal cancer." (PMID 27999563, 2016). "In this study, we assessed the effects of BANCR expression on colorectal cancer cell phenotypes in vitro and in vivo, and we showed that BANCR suppressed colorectal cancer cell growth through interaction with P21 protein." (PMID 25928067, 2015).
colorectal cancer (continued). "This study advances our understanding of the role of BANCR as a regulator of the pathogenesis of colorectal cancer and facilitates the development of lncRNA for future studies in colorectal cancer." (PMID 25928067, 2015). "Our clinical data indicated that BANCR expression was inversely related to colorectal cancer progression." (PMID 25928067, 2015). "Significantly, the expression of BANCR was down-regulated in colorectal cancer tissues compared with normal tissues." (PMID 25928067, 2015). "We found that p21 knockdown partially compromised the effects of BANCR over-expression on colorectal cancer growth inhibition." (PMID 25928067, 2015). "We next validated the effects of BANCR over-expression on the proliferation of colorectal cancer cells in vivo." (PMID 25928067, 2015). "In this study, we show that BANCR expression was significantly down-regulated in colorectal cancer tissues compared with normal tissues, and overexpression of BANCR suppressed colorectal cancer cell growth in vitro and in vivo." (PMID 25928067, 2015). "The results indicated that the effect of BANCR on colorectal cancer is at least in part through targeting P21." (PMID 25928067, 2015). "Taken together, our findings suggest that down-regulation of BANCR contributes to the proliferation of colorectal cancer cells, at least in part, through the regulation of p21 protein." (PMID 25928067, 2015). "qRT-PCR analysis was used to examine BANCR levels in 38 colorectal cancer tissues and 38 matched normal colorectal tissues." (PMID 25928067, 2015). "To further confirm that P21 was involved in the BANCR-induced decrease in colorectal cancer cell proliferation, we performed rescue experiments." (PMID 25928067, 2015). "Moreover, BANCR has been shown to be diminished in colorectal cancer tissues compared with unaffected sample." (PMID 34409032, 2021). "In contrast, BANCR was shown to be decreased in bladder cancer and colorectal cancer." (PMID 30200918, 2018). "Furthermore, knockdown of P21 impaired the effects of BANCR overexpression on cells’ growth inhibition, indicating that BANCR inhibited the growth of Colorectal cancer cells through targeting on P21." (PMID 29212285, 2017). "In other word, overexpression of BANCR suppressed colorectal cancer cell proliferation." (PMID 29212285, 2017). "Besides, downregulation of BANCR promotes colorectal cancer cell proliferation through decreasing expression of p21 protein." (PMID 27514530, 2016). "To determine whether the effects of BANCR on the proliferation of colorectal cancer cells were mediated by inhibition of cell cycle progression, we followed cell cycle progression in SW480 and HCT116 cells with flow cytometry." (PMID 25928067, 2015). "However, in our study, we found that the expression of BANCR was significantly downregulated in colorectal cancer tissues, and it is likely to be due to individual difference." (PMID 25928067, 2015). "In summary, in this study, we have shown that BANCR is downregulated in colorectal cancer tissues." (PMID 25928067, 2015). "Next, BANCR expression was detected by qRT-PCR in 4 human colorectal cancer cell lines." (PMID 25928067, 2015). "Therefore, we investigated the involvement of BANCR in the proliferation of colorectal cancer cells." (PMID 25928067, 2015). "The observations made with the shRNA indicated that lower BANCR expression may contribute to colorectal cancer progression." (PMID 25928067, 2015). "Additionally, we observed that 3 colorectal cancer cell lines exhibited low BANCR expression, which corroborate our colorectal cancer tissues findings." (PMID 25928067, 2015). "Taken together, BANCR treatment could induce colorectal cancer cell apoptosis and G0/G1 phase arrest." (PMID 25928067, 2015). "However, little is known concerning the role of BANCR in the development of colorectal cancer (CRC)." (PMID 25013510, 2014). "Similarly, a study on colorectal cancer cells reported that BANCR acts as a miR-203 sponge." (PMID 38137560, 2023).
colorectal cancer (continued). "However, another research elucidated a contradictory result showing that BANCR expression was lowered in colorectal cancer tissues, and enforced expression of BANCR repressed colon cancer cell growth in vitro and in vivo, indicating its tumor-suppressing property." (PMID 30144787, 2018). "Additionally, it has been reported that the expression of BANCR is increased in colorectal cancer (CRC) and that BANCR could strengthen the migration and proliferation abilities of CRC by inducing epithelial-mesenchymal transition (EMT) via the activation of the MEK/ERK signaling pathway." (PMID 32907530, 2020). "In some cancer types such as colorectal cancer, hepatocellular carcinoma and papillary thyroid carcinoma, there is no agreement about BANCR expression, necessitating the importance of additional functional studies in these tissues." (PMID 34409032, 2021). "Moreover, in some cancers such as colorectal cancer, hepatocellular carcinoma and papillary thyroid carcinoma, there is no agreement on the expression of BANCR, and its biological function is still unclear." (PMID 38137560, 2023).
gastric cancer (20 papers, 2016 to 2025). A primary or metastatic malignant neoplasm involving the stomach. "Increased expression of lncRNA BANCR is associated with clinical progression and poor prognosis in gastric cancer." (PMID 31147452, 2019). "Subsequent research found that BANCR expression is abnormal in various cancers, including bladder cancer, colorectal cancer, endometrial cancer, gastric cancer, and hepatocellular carcinoma." (PMID 39894218, 2025). "miR-9 has been shown to target NF-κB1, therefore anta-miR-9 has upturned the impact of BANCR on gastric cancer cell proliferation and death." (PMID 34409032, 2021). "BANCR silencing has blocked gastric cancer growth and boosted apoptosis possibly through decreasing NF-κB1 (P50/105) levels and activity." (PMID 34409032, 2021). "The miRNA miR-9 regulates the growth of cancer cells, and BANCR and miR-9 mutually regulate by altering the activity of nuclear factor (NF)-κB in gastric cancer cells." (PMID 32593310, 2020). "In a world, NF-κB1 and miR-9 were involved in the growth and apoptosis of gastric cancer cells mediated by BANCR." (PMID 29212285, 2017). "Deregulated expression of BANCR was found in lung cancer, colorectal cancer, gastric cancer and bladder cancer." (PMID 29383102, 2017). "At the same time, BANCR expression attached overall survival in gastric cancer patients, indicating BANCR was an independent poor prognostic factor for gastric cancer patients." (PMID 29212285, 2017). "Knockdown of BANCR inhibited Gastric cancer cell growth and promoted cell apoptosis via a significant decrease of NF-κB1 (P50/105) expression and 3’UTR of NF-κB1 activity." (PMID 29212285, 2017). "In gastric cancer, BANCR expression was increased in tumor tissues compared with paired adjacent normal tissues." (PMID 26758762, 2016). "Moreover, BANCR significantly increased and enhanced the resistance of gastric cancer cells to cisplatin by stimulating the extracellular signal–regulated kinase 1/2 pathway." (PMID 39894218, 2025). "Another functional study has demonstrated up-regulation of BANCR in gastric cancer cells." (PMID 34409032, 2021). "One study reported that, in gastric cancer cells, downregulation of BANCR decreased NF-κB activity and inhibited cell proliferation while promoting apoptosis, whereas overexpression of NF-κB—a target of miR-9 that regulates cancer cell growth—and inhibition of miR-9 reversed these effects." (PMID 32593310, 2020). "In addition, abnormal expression of BANCR has been investigated in various types of cancer such as gastric cancer, retinoblastoma, and non-small cell lung cancer." (PMID 28969673, 2017). "Knockdown of miR-9 also reversed the effects of BANCR on gastric cancer cell growth and apoptosis." (PMID 29212285, 2017). "In GC cells, a high expression level of BANCR was found to mediate gastric cancer cell cisplatin resistance by increasing the phosphorylation of the ERK protein." (PMID 38927012, 2024). "In addition, a growing body of literature has reported that aberrant BANCR expression could be detected in breast cancer, gastric cancer, esophageal cancer, hepatocellular carcinoma, endometrial cancer, retinoblastoma and osteosarcoma." (PMID 32907530, 2020). "For example, analysis of the prognostic value of a single lncRNA from qRT-PCR array of 84 gastric cancer patient samples found that higher level of BANCR could predict a poor prognosis for GC patients." (PMID 34257533, 2021). "The research discovered significant increase of plasma lncRNA (TINCR, CCAT2, AOC4P, BANCR, and LINC00857) in gastric cancer cell lines." (PMID 33473276, 2021). "Additionally, accumulating studies have suggested that BANCR is correlated with the metastasis and invasion of multiple tumor cells and could function as a prognostic biomarker for cancers such as gastric cancer, hepatocellular carcinoma, renal cell carcinoma and non-small cell lung cancer." (PMID 32907530, 2020).
gastric cancer (continued). "Similarly, lncRNAs, such as H19, TINCR, AOC4P, BANCR, LINC00857, and CCAT2, are detectable in body fluids and can be used to efficiently differentiate gastric cancer patients from healthy controls." (PMID 34885213, 2021).
lung carcinoma (17 papers, 2016 to 2025). "BANCR appears to be associated with tumorigenesis, and is dysregulated in colorectal, bladder, gastric, papillary thyroid, and lung cancer, and in ESCC, osteosarcoma, and hepatocellular carcinoma." (PMID 28009984, 2017). "Up-regulating BANCR was tightly linked with radiotherapy for lung cancer." (PMID 33892664, 2021). "In Lewis lung cancer cells, it was found that histone deacetylation played a role in controlling BANCR." (PMID 39912974, 2025). "BANCR has been reported to function as a tumor suppressor in lung cancer while acting as an oncogene in various types of cancer." (PMID 27462868, 2017). "Additionally, lncRNA BANCR in the OS model has been reported to function as an oncogene or tumor suppressor gene, which was often dysregulated in human cancers, including lung cancer." (PMID 35069738, 2022). "However, four independent studies in lung cancer have verified the role of BANCR silencing in suppression of tumor growth or metastatic ability, demonstrating a tumor suppressor role for this lncRNA in this type of cancer." (PMID 34409032, 2021). "In contrast, decreased expression of BANCR has been found in both colorectal and lung cancers." (PMID 27514530, 2016). "However, BANCR may function as a tumor suppressor in lung cancer, and conclusions from two papillary thyroid cancer studies were contradictory." (PMID 28009984, 2017). "BANCR silencing saved the inactivation of p38 MAPK and JNK to contribute to the migration and proliferation of lung cancer." (PMID 39912974, 2025). "In the differentially expressed lncRNAs, BANCR, kucg 1, MALAT1, NEAT1 were chosen for further study in lung cancer." (PMID 28938549, 2017). "Compared with breast adjacent tissues, AFAP1-AS1, PVT1, HYMAI were downregulated in most breast cancer tissues, and lncRNA PVT1, BANCR, HCG18 were upregulated in lung cancer." (PMID 28938549, 2017). "Using the same method, the expression of lncRNAs MALAT1, BANCR, NEAT1 in primary lung cancer were also analyzed." (PMID 28938549, 2017). "Besides, some lncRNAs have been recognized as a novel biomarker, for instance, BANCR in gastric carcinoma, HOTAIR in colorectal carcinoma, and MALAT1 in lung cancer." (PMID 33892664, 2021).
thyroid cancer (14 papers, 2017 to 2025). "In addition, the long non-coding RNAs (lncRNAs) associated with thyroid cancer include BANCR, FTCSC3 and Ak023948." (PMID 30641858, 2019). "For example, in a study of the xenograft model of thyroid cancer, the upregulation of BANCR enhanced tumor growth; in another study on IHH-4 thyroid cancer cells, BANCR enhanced proliferation, prevented apoptosis and G1 arrest, and induced autophagy." (PMID 38137560, 2023). "Specific to thyroid cancer, BANCR was found to be uniquely expressed both in PTC cells in vitro and in tumor samples derived from PTC patients as compared to normal controls." (PMID 35846375, 2022). "The expression of BANCR was positively related to the pathological stage of thyroid carcinoma and lymph node metastasis." (PMID 32596158, 2020). "Furthermore, BANCR/TSHR signaling overexpression can significantly inhibit the luteolin antitumor impacts on thyroid cancer in vivo and in vitro and, as a result, can act as an essential anticancer agent for thyroid cancer through suppressing the BANCR/TSHR pathway." (PMID 33805687, 2021). "Sedaghati summarized the dysregulated and functional LncRNAs in thyroid cancer, including 28 upregulated LncRNAs, such as ANRIL, BANCR, H19, HOTAIR, MALAT1, and NEAT1, and 22 downregulated LncRNAs, including GAS5, NAMA, PTCSC2, and PTCSC3." (PMID 37874339, 2024). "Several lncRNAs, such as MALAT1, BANCR, and PTCSC3, have been identified to promote the proliferation and metastasis of thyroid cancers." (PMID 38298184, 2023). "In thyroid cancer, several lncRNAs, such as MALAT1, H19, BANCR, and HOTAIR have been identified as contributing factors to tumor development, and used as novel biomarkers for early diagnosis or treatment." (PMID 34404767, 2021). "In thyroid cancer, several lncRNAs, such as MALAT1, H19, BANCR, HOTAIR have been identified as contributing factors to the development of cancer." (PMID 34404767, 2021). "The study showed that BANCR can be recruited by EZH2 to increase the expression level of thyroid-stimulating hormone receptor (TSHR) and promote the proliferation of IHH-4 thyroid cancer cells." (PMID 32596158, 2020). "A qRT-PCR analysis revealed that BANCR is highly expressed in PTC tissue compared with normal tissue; it was also found to promote proliferation, inhibit cell apoptosis, alleviate G1 arrest, and stimulate autophagy in IHH-4 thyroid cancer cells." (PMID 32593310, 2020).